CRP (C-reactive protein)
Diseases named in the same sentence as CRP in open-access papers (continued):
Sharing a sentence is not in itself a finding about the gene and the disease.
Neonatal sepsis (continued). "In addition to clinical signs and symptoms, blood culture and a range of biomarkers including C-Reactive Protein (CRP), procalcitonin (PCT), albumin and IL-6 have been proposed and utilised for the diagnosis of neonatal sepsis." (PMID 39937751, 2025). "In term infants born after prolonged rupture of membranes but not diagnosed with early-onset neonatal sepsis, median CRP was low but with outliers above 60, 80, and 90 mg/L after 1, 12, and 36 h." (PMID 41441318, 2025). "The results of this retrospective study outline the feasibility of using procalcitonin and CRP measured on the first day in order to increase the detection rate of early-onset neonatal sepsis, in the absence of positive blood cultures." (PMID 38255436, 2024). "Two normal CRP values obtained 8–24 h after birth and 24 h later have a negative predictive value of 99.7% for proven neonatal sepsis and are helpful for discontinuing antibiotics." (PMID 39858292, 2024). "The accurate early diagnosis of neonatal sepsis remains difficult, as signs and symptoms are non-specific, and widely used blood markers such as C-reactive protein (CRP) are also non-specific and evolve over time." (PMID 36769133, 2023). "Out of all the laboratory values tested, only the counts of the leukocytes and thrombocytes, the percentages of immature neutrophils and lymphocytes, the presence of toxic changes in neutrophils, and the serum concentrations of CRP and PCT acted as significant for diagnosing neonatal sepsis." (PMID 36834338, 2023). "During this research, the data also exhibited a high sensitivity (93%) and a low specificity (37%) of CRP in diagnosing neonatal sepsis (data not shown)." (PMID 37197571, 2023). "Traditional laboratory biomarkers that are used in neonatal sepsis, such as C-reactive protein (CRP) and procalcitonin tests, are not effective alone as laboratory markers." (PMID 36010061, 2022). "Therefore, it is of interest to assess the role of serial CRP and Total Leukocyte Count (WBC) in neonatal sepsis and to compare with blood culture." (PMID 37654832, 2022). "IL-6 has been shown to be superior to CRP in the diagnosis of late-onset neonatal sepsis due to coagulase-negative staphylococci." (PMID 35345614, 2022). "Serial CRP and WBC measurements are useful in the diagnosis of neonatal sepsis." (PMID 37654832, 2022). "ROC curves for the ability of RIP3, hs-CRP and PLT to predict neonatal sepsis were constructed." (PMID 34488677, 2021). "CRP/MPV is an easily calculated ratio which could be used as a simple and accurate marker for the diagnosis of late-onset neonatal sepsis." (PMID 34676267, 2021). "Recently, CRP/albumin ratio is used as a potential marker for gram-negative bacteremia in late-onset neonatal sepsis." (PMID 34676267, 2021). "The authors found that, although PCT is more sensitive than CRP, the use of PCT or CRP alone cannot rule out a diagnosis of neonatal sepsis." (PMID 34830040, 2021). "Although not specific for neonatal sepsis, CRP has the highest sensitivity, specificity, high negative predictive value, and positive predictive value." (PMID 34899922, 2021). "In another study it was shown that presepsin alone had a high sensitivity and specificity to diagnose neonatal sepsis, which did not change in combination with CRP and/or PCT." (PMID 34079538, 2021). "Garland and Bowman assessed the usefulness of C-reactive protein (CRP) either alone or in combination with a full blood examination (FBE) and microbiology of gastric aspirate in predicting the diagnosis of neonatal sepsis compared with routinely available markers of infection." (PMID 34899922, 2021). "Although the CRP shows its usefulness in the diagnosis of neonatal sepsis, it does not substitute the microbiological culture." (PMID 32238170, 2020). "In literature we could not find a study included the pairwise comparison of the performance of the parameters of CRP, MPV and PCT in premature neonatal sepsis patients." (PMID 30068303, 2018).
Neonatal sepsis (continued). "Therefore, the objective of this study was to evaluate the significance of CRP and WBC count in the diagnosis of neonatal sepsis." (PMID 30069260, 2018). "CRP estimation does have a role in the diagnosis of neonatal sepsis but the test is not specific enough to be relied upon as the only indicator." (PMID 26150837, 2015). "Humoral and cellular systems are activated in the first hours of neonatal sepsis, various molecules such as Interleukin-6 (IL-6), Procalcitonin (PCT), C-reactive protein (CRP), and IL-8 released in the serum which mediated the host response to bacterial infection." (PMID 25996378, 2015). "Neonates with gram negative sepsis had significantly higher rates of positive CRP than neonates with gram positive neonatal sepsis and neonates with negative blood culture." (PMID 25280754, 2014). "CRP and PCT have been proved to be useful biomarkers for the diagnosis of neonatal sepsis." (PMID 23984377, 2013). "In conclusion, although the clinical manifestations of neonatal sepsis are often non-specific, CBC-derived inflammatory markers—particularly CRP, PLR, and NLR—may contribute to improved diagnostic accuracy, especially in late-onset cases." (PMID 40564645, 2025). "This poses the same dilemma as CRP as these studies reflect neonatal sepsis, as opposed to neo-VAP." (PMID 38698211, 2024). "In cases of neonatal sepsis, Fan and Yu (2012) did not recommend the isolated use of inflammatory markers CRP, PCT, interleukin-8 (IL-8), TNF-α and interleukin-1 beta (IL-1β); although IL-6 was rated as superior in relation to the majority of markers, it should not be used in isolation." (PMID 34846061, 2022). "Also, PSP is more sensitive and specific and has a good negative predictive value compared to CRP confirming its value as marker to rule out early onset neonatal sepsis." (PMID 27689072, 2016). "CRP is an acute-phase protein found in the blood that is produced by the liver because of infection or tissue injury, while PCT is a 116-amino acid peptide involved as a precursor in calcium homeostasis, and both of them have been widely used as useful markers for the diagnosis of neonatal sepsis." (PMID 23984377, 2013). "However, as the CRP elevation is known to be delayed for a considerable time, the sensitivity of the initial CRP concentration will probably never be high enough to suffice as a sole parameter for detecting neonatal sepsis and needs to be combined with other parameters, such as IL-6." (PMID 36233706, 2022). "Consistent with the data reported in the literature, our results show that standard laboratory tests (CBC, CRP, PCT) lack specificity due to poor positive predictive value and should not be used alone to diagnose early neonatal sepsis." (PMID 40150637, 2025). "Serial measurement of CRP and Total leukocyte count (WBC) neonates with clinicalsymptoms can be considered promptly for diagnosis of neonatal sepsis would be rather than single measurement." (PMID 37654832, 2022). "At present, the early diagnosis of neonatal sepsis in practice depends mainly on nonspecific infection indicators such as WBC, PLT, CRP and PCT." (PMID 34488677, 2021). "We observed that although PCT is more sensitive than CRP, the use of PCT or CRP alone cannot rule out a diagnosis of neonatal sepsis." (PMID 30463590, 2018). "Some studies have shown that PCT is more reliable than CRP as a test for the diagnosis of early-onset neonatal sepsis, but other studies have not found any advantage of PCT over CRP." (PMID 17324267, 2007). "It has been shown that serial C-reactive protein (CRP) measurements increase its sensitivity and negative predictive value for neonatal sepsis, and may be beneficial for assessing the treatment response of affected neonates under antibiotic therapy." (PMID 38255436, 2024).
Neonatal sepsis (continued). "But sometimes, some of the doctors come during [early onset neonatal sepsis] treatment and if they notice the preterm newborns have no fever then they decide to do a CBC, CRP [blood tests for complete blood count and C-reactive protein (to test for inflammation or infection)]." (PMID 37124770, 2023). "A set of investigations including CRP, TLC, ANC, thrombocytopenia, cytoplasmic vacuolization in the neutrophils, and gastric aspirate for polymorphs are highly sensitive in the detection of culture-negative cases of neonatal sepsis." (PMID 34899922, 2021). "For PCT and CRP, the summary LRP and LRN for index testing were on the right lower quadrant (RLQ), indicating that PCT or CRP could not exclude or confirm neonatal sepsis." (PMID 30463590, 2018). "In the VLBW infants with late-onset neonatal sepsis CEACAM1 expression on the CD4+ T-cells correlated with the maximal CRP levels, while in children with meningococcal septic shock serum soluble CEACAM1 concentrations did not correlate with CRP." (PMID 23894299, 2013). "At a cut-off value, 12 mg/l CRP was found to have a sensitivity of 45%, specificity of 95%, positive predictive value (PPV) of 30%, negative predictive value (NPV) of 30% for the diagnosis of neonatal sepsis." (PMID 23493845, 2012). "For PCT + CRP, the summary LRP and LRN for index testing was between the left lower quadrant (LLQ) and right lower quadrant (RLQ), suggesting that PCT + CRP may exclude but not confirm neonatal sepsis." (PMID 30463590, 2018).
Pleural effusion (184 papers, 1998 to 2026). The presence of an excessive amount of fluid in the pleural cavity. "In the base model, the total scores of pleural effusion, lung consolidation, pulmonary atelectasis, and CRP were associated with an increased risk of RMPP." (PMID 39945309, 2025). "While elevated CRP levels, low lymphocyte count, and reduced albumin levels were associated with pleural effusion, only lymphocyte count (cut-off < 0.605 109/L) remained an independent predictor in the multivariate analysis." (PMID 40428888, 2025). "Age >60 years, presence of pleural effusion, chemotherapy, and CRP > 14.1 mg/dL were found to be independent risk factors for mortality in proven IPA patients." (PMID 38436032, 2024). "In light of this, this study was conducted to identify the efficacy of pleural fluid CRP as a diagnostic biomarker in distinguishing between the etiologies of exudative pleural effusions." (PMID 35874904, 2022). "We used the ROC curve to determine the diagnostic performance of pleural fluid CRP in the differential diagnosis of exudative pleural effusions." (PMID 35874904, 2022). "Pleural effusion volume quantified on chest CT examination positively associated with the duration of hospitalization, CRP levels, as well as Ranson, BISAP, Marshall, APACHE II, CTSI, and EPIC scoring systems." (PMID 34727802, 2021). "Among nivolumab‐treated patients with NSCLC with good PS, the univariate analysis revealed that smoking status, driver mutation, LDH, CRP, liver metastasis, pleural effusion, and steroid use were significantly associated with PFS." (PMID 31880861, 2020). "We aimed to determine the presepsin concentration in pleural fluid from patients with pleural effusions of different aetiologies and to compare its diagnostic value with that of pleural fluid C-reactive protein (CRP) and procalcitonin (PCT)." (PMID 30470216, 2018). "Several other studies have investigated the relationship between pleural fluid CRP and the cause of pleural effusions, with similar findings." (PMID 30470216, 2018). "The main strengths of this study are that it demonstrates the diagnostic value of pleural CRP measurements in a large cohort of patients with varying etiologies for pleural effusion." (PMID 27194820, 2016). "The nomogram model constructed in this study indicated that three risk factors- C-reactive protein (CRP) > 20 mg/L, pleural effusion, and high Lactate Dehydrogenase (LDH) levels- could be used for the early identification of PB in children with RMPP." (PMID 41988148, 2026). "Finally, pleural effusion, lung consolidation, pulmonary atelectasis, and CRP were identified as independent risk factors for RMPP." (PMID 39945309, 2025). "Pleural effusions, venous thrombosis, and CRP elevation were identified as potential risk factors." (PMID 30652419, 2019). "This main objective of the study was to determine whether PCT is superior to white cell count and C-reactive protein when distinguishing between pleural infection and other causes of unilateral pleural effusion in adults." (PMID 28158976, 2017). "Pleural effusion was associated with higher CRP greater than 100 mg L−1 (P < 0.001)." (PMID 24118607, 2014). "By means of multiple logistic-regression analyses, we determined the additional diagnostic power of measurement of BNP and CRP, patients' age, systolic blood pressure, S3 gallop, left ventricular ejection fraction, and the presence of pleural effusion on the chest radiograph." (PMID 21696613, 2011). "Moreover, when the underlying cause of a pleural effusion is obscure, a high pleural CRP level combined with pleural neutrophil predominance, lower pleural glucose, and lower pleural pH may shift the diagnosis towards an infectious etiology." (PMID 27194820, 2016). "Both serum CRP (CRPs) and pleural fluid CRP (CRPpf) have been shown to aid in distinguishing between different types of pleural effusion (PE)." (PMID 42016339, 2026).
Pleural effusion (continued). "SHAP analysis identified the retinol-binding protein 4 level, M. pneumoniae cycle-threshold value, D-dimer level, fever duration before admission, C-reactive protein-to-albumin ratio, and presence of pleural effusion as key predictors." (PMID 42112459, 2026). "When pleural effusion, lung consolidation and pulmonary atelectasis were present and CRP was 70 mg/L in BALF, the scores were 22, 22, 20, and 50, respectively, with a total score of 102, corresponding to a risk value for RMPP >0.7." (PMID 39945309, 2025). "Strong but unlisted signals were observed for pleural effusion, elevated C-reactive protein, hypokalemia, and central nervous system lesions." (PMID 40137538, 2025). "In univariate logistic analysis, atelectasis, pleural effusion, high neutrophil level, high CRP level, high D-dimer level, high LDH level, and low serum albumin level were remarkably associated with the risk of developing RMPP." (PMID 40654577, 2025). "through multivariate logistic regression analysis, found that NLR, IL-6, CRP, LDH, D-dimer, pulmonary necrosis, pleural effusion, and pericardial effusion are all risk factors for embolism in children with RMPP." (PMID 40171163, 2025). "The patient showed significant clinical improvement with vancomycin, evidenced by CRP trends and resolution of pleural effusion on imaging." (PMID 40115676, 2025). "The results showed that pleural effusion, lung consolidation, pulmonary atelectasis, and CRP were all independent risk factors for predicting RMPP, with CRP contributing the most to the model." (PMID 39945309, 2025). "In this study, the proportion of children with hyperthermia or adverse pulmonary imaging features (pleural effusion, lung consolidation, and pulmonary atelectasis) and biochemical indices (CRP and AST) levels were significantly higher in the GMPP group." (PMID 39945309, 2025). "Our study further confirmed that elevated inflammatory markers such as CRP, LDH, neutrophils (%), IL-6, ESR, lung consolidation, combined pleural effusion were risk factors for RMPP." (PMID 40656195, 2025). "In the second year of treatment, when pleural effusion was diagnosed, the CRP level had increased to 64.33 mg/L." (PMID 41156568, 2025). "Six variables were included in the logistic regression analysis by obtaining variables with p < 0.01 in the univariate analysis, including high‐grade fever, pleural effusion, lung consolidation, pulmonary atelectasis, CRP, and AST." (PMID 39945309, 2025). "NP should be considered in children with large consolidations on lung imaging with concomitant persistent high fever; significantly increased levels of CRP, procalcitonin, and other inflammatory indicators; and pleural effusion." (PMID 40399899, 2025). "In the pleural effusion group, C-reactive protein and LDH levels were significantly higher, suggesting a potential relationship with the degree of the inflammatory reaction." (PMID 40433479, 2025). "Bedside chest X-ray suggested progression of exudation and consolidation in both lungs, along with bilateral pleural effusion (and IL-6: 5938 pg./mL, CRP: 322 mg/L)." (PMID 41169424, 2025). "The albumin/globulin (A/G) ratio was also lower in the pleural effusion group (median 1.05 vs. 1.16, p = 0.027), while the CRP/albumin (CRP/A) ratio was significantly higher in patients with pleural effusion (2.84 vs. 0.839, p < 0.001)." (PMID 40428888, 2025). "Postoperatively, the mother’s respiratory symptoms worsened, diastolic dysfunction progressed, and imaging revealed bilateral pleural effusion with right lung opacities, accompanied by elevated levels of C-reactive protein (CRP), an inflammatory marker." (PMID 40718209, 2025). "Despite the treatment, there was no improvement in the patient’s inflammatory response (WBC, 13,920/μL; Neut, 88.1%; CRP, 16.42 mg/dL), and CT revealed pleural effusion with encapsulation on the eighth hospital day." (PMID 39517010, 2024).